RNU6-1340P (RNA, U6 small nuclear 1340, pseudogene)
Gene: Small nuclear RNA gene on chromosome 16 (19,012,157 to 19,012,263, forward strand). Ensembl gene ENSG00000207167.
Homologues: Orthologues: chimpanzee U6 (99% identical), macaque U6 (95% identical), dog U6 (81% identical). Paralogues in human: RNU6-1091P (90% identical), RNU6-11P (90% identical), RNU6-37P (90% identical), RNU6-17P (89% identical), RNU6-18P (89% identical), RNU6-222P (89% identical), RNU6-737P (89% identical), RNU6-774P (89% identical), RNU6-1 (88% identical), RNU6-128P (88% identical), RNU6-12P (88% identical), RNU6-13P (88% identical), and 1290 more.